MMP9 (matrix metallopeptidase 9)
Diseases named in the same sentence as MMP9 in open-access papers (continued):
Sharing a sentence is not in itself a finding about the gene and the disease.
Hypertension (continued). "Whether altered MMP9 function is secondary to the vascular remodeling of the resistance arteries as seen in hypertension or MMP9 contributes to the development of hypertension by inducing vascular remodeling is incompletely understood." (PMID 25314291, 2014). "Similarly, in the SHR, circulating levels of MMP-9 are increased compared with normotensive rats, which suggests that in hypertension the activity MMPs is up-regulated and contributing to vascular remodeling." (PMID 25535075, 2014). "Both HCRP and MMP9 are sensitive biomarkers which may reflect destabilization and complication of atherosclerotic plaques early in the hypertension." (PMID 23606891, 2013). "Furthermore, the cardio-protective effects of SalA on SHRs provide sufficient evidence to support the development of SalA as a novel MMP-9 inhibitor against cardiac fibrosis, abnormalities induced by hypertension." (PMID 23533637, 2013). "Our observations support the hypothesis that inadequate mobilization of BM-derived stem and progenitor cells in hypertension results from impaired NOS/NO/MMP9 signalling in BM, a condition that may be corrected with pharmacological intervention." (PMID 23554866, 2013). "While there is a number of experimental or cross-sectional studies in selected populations that associates elevated levels of MMP-9 to CAD risk factors before onset of disease e.g. smoking, alcohol, and hypertension, little is still known about the distribution of MMP-9 in the general population." (PMID 18335048, 2008). "Finally, voxel-wise determined IgG staining intensity correlated positively with perivascular MMP9 in periventricular NAWM and WMH in individuals with hypertension and control individuals, suggesting a close association between BBB damage and vascular remodeling/inflammation." (PMID 40219923, 2025). "MMP-2, MMP-9, and ADAM17 have been implicated in the degradation of the endothelial barrier, leading to the increased permeability of the endothelium and the recruitment of inflammatory cells, which further promotes progression of vascular remodeling and hypertension." (PMID 40492135, 2025). "Therefore, MMP9, HIF1A, and BCL2 are closely linked to the onset and progression of hypertension, and catechin components may deliver their anti-hypertensive benefits through interactions with these target proteins." (PMID 39272451, 2024). "However, research indicates that heightened levels of MMP-9 may have a key role in the development of arterial stiffness and high blood pressure." (PMID 38357561, 2023). "The MMP-9/TIMP-1 ratio (an index of net MMP-9 activity) is associated with great arterial stiffness, as assessed by carotid-femoral pulse wave velocity, but not with muscular arterial elasticity, as assessed by carotid-radial pulse wave velocity (CRPWV), in patients with hypertension." (PMID 33923477, 2021). "We suggest that increased plasma MMP-9 activity may be related to hypertension." (PMID 33081182, 2020). "Moreover, the high MMP-9 level may exhibit effects on drug resistance of beta-blockers, a class of medications that are commonly used for hypertension treatment." (PMID 29693002, 2018). "MMP2 and MMP9 are two major matrix metalloproteinases and involve in digesting extracellular matrix in placenta; loss of function of MMP2 and MMP9 are associated with un-remodeling spiral vessel, hypertension, compromised trophoblast invasion and preeclampsia during pregnancy." (PMID 28959722, 2017). "MMP-2 concentrations were 1.02, 1.03 and 1.05 times, and MMP-9 concentrations were 1.03, 1.06 and 1.07 times greater for 1 unit increase in log-transformed water, hair and nail arsenic concentrations, respectively, after adjusting for covariates (age, sex, BMI, smoking habit and hypertension)." (PMID 26637202, 2015).
Hypertension (continued). "Experimental hypertension studies have reported that the intima and media thickness ofconduct vessels was associated with increased expression of MMP-9 and MMP-2, and thisevent could be prevented with non-selective MMP inhibitor (doxycycline)treatment." (PMID 26039662, 2015). "For example, knock out of MMP-2 and MMP-9 by CRISPR/Cas9 system in animal models results in reduced hypertensive responses, highlighting its critical role in the development of hypertension." (PMID 40492135, 2025). "We found that voxel-wise area of IgG positively correlated to αSMA intensity (ρ = 0.312, p < 0.001) and intensity of perivascular MMP9 in periventricular NAWM and WMH of individuals with hypertension and control individuals (ρ = 0.370, p < 0.001)." (PMID 40219923, 2025). "Voxel-wise intensity of perivascular MMP9 in periventricular NAWM and WMH of individuals with hypertension and control individuals positively correlated to αSMA staining intensity (ρ = 0.304, p < 0.001)." (PMID 40219923, 2025). "Cerebral production of Cyclophilin A (CyPA) is induced in hypertension and after TBI, and it was demonstrated to activate the nuclear factor-κB (NF-kB)- matrix-metalloproteinase-9 (MMP-9) pathway in cerebral vessels leading to BBB disruption." (PMID 38073626, 2023). "We demonstrate here that mTBI leads to a significant increase in cerebral NF-kB expression, enhanced production and activation of MMP-9 and attenuated expression of the BBB protein ZO-1 in hypertension, which were prevented by cyclosporine treatment." (PMID 38073626, 2023). "Of these, TNF, MMP9, and AKT1 have been reported to be involved in hypertension and considered important genes that function in the effect of gastrodin on hypertension." (PMID 37495624, 2023). "Hypertension has many complications whichcan increase MMP-9 activity in plasma and tissues, and MMP-9 was detected to be involved in occurrence of the retinal complicationsof hypertension." (PMID 37886137, 2023). "Eucalyptol significantly decreased the increased plasma levels of MMP-9 and TIMP-1 in chronic nicotine-induced hypertension inrats and its combination with lisinopril exerted more significant effects compared to each drug alone." (PMID 37886137, 2023). "In conclusion, eucalyptolsignificantly decreased the increased plasma levels of MMP-9 and TIMP-1 in nicotine-induced hypertension in rats." (PMID 37886137, 2023). "This study aims to further explore and analyze the effects of valsartan and valsartan treatment of sacubitril on vascular endothelial function, APN, MMP-9, and BNP levels in patients with hypertension and chronic heart failure based on previous research." (PMID 35222898, 2022). "A correlation study in children with obesity hypertension showed the induction of plasma levels of MMP-2 and MMP-9 in patients with obese." (PMID 36034923, 2022). "We further found that intragastric administration of curcumin attenuated hypertension, repressed NF-κB activation, NLRP3 and MMP-9 expressions in the aortas, reduced the media thickness and the ratio of media thickness to lumen diameter in the aortas of SHR." (PMID 35530510, 2022). "To further clarify the therapeutic mechanisms of TTR on pregnant hypertension, we investigated the MMP‐2 and MMP‐9 expressions in placental tissues." (PMID 32533762, 2020). "Individuals with T2DM in combination with arterial hypertension exhibit maximum TIMP-1 levels and TIMP-1:MMP-2 and TIMP-1:MMP-9 ratios, as well as enhanced secretion of tumor necrosis factor alpha (TNF-α), interleukin-16 (IL-6), and IL-17." (PMID 33419373, 2020). "Age, hypertension, and CHADS2-VASc2 score were identified as predictors of MMP-9 elevation by univariate analysis." (PMID 31878008, 2019). "MMP-9 levels were correlated to age, arterial hypertension, CHA2DS2-VASc score as a possible illustration of the complex network linking aging, hypertension, and atrial remodeling." (PMID 31878008, 2019).
Hypertension (continued). "Similarly, whether patients complicated with hypertension showed higher MMP-9 levels was verified." (PMID 29693002, 2018). "Another study found that arterial remodeling, observed in an animal model of Hhcy-induced arterial hypertension, was in part due to increased MMP-2 and MMP-9 activation." (PMID 28133545, 2017). "MMP-9, similar to MMP-2 is induced at the early stages of hypertension, and this is probably favorable to alleviate the initial vascular tensile stress." (PMID 27490532, 2016). "In patients with hypertension, it has been found that the plasma levels and activity of MMP-2 and MMP-9 can be increased, decreased, or unchanged." (PMID 27490532, 2016). "In the same model of hypertension, the inhibition of NF κB resulted in the reduction of the transcription rate of MMP-2, MMP-9 and ROS production." (PMID 25535075, 2014). "This study aimed to explore the correlation between HCRP, MMP9, and TCM syndrome and to analyze the possibility of using HCRP and MMP9 to help TCM syndrome classification in hypertension." (PMID 23606891, 2013). "In a recent human study, elevated plasma MMP-9 level correlated with systolic BP, however, elevation of plasma MMP-2 and -10 had better correlation with hypertension-induced renal damage." (PMID 24159376, 2013). "The current study focuses on HCRP, MMP9, and TCM syndrome in an attempt to determine the relationship between TCM syndrome and inflammatory biomarkers in patients with essential hypertension." (PMID 23606891, 2013). "We showed that voxel-wise intensity of extravasated IgG positively correlated with perivascular MMP9 in periventricular NAWM and WMH of individuals with hypertension and control individuals, suggesting an overall interplay between BBB damage and neurovascular inflammation." (PMID 40219923, 2025). "We found that voxel-wise intensity of IgG staining in periventricular NAWM and WMH of individuals with hypertension and control individuals positively correlated to GLUT1 staining intensity (ρ = 0.238, p < 0.001) and area of perivascular MMP9 (ρ = 0.290, p < 0.001)." (PMID 40219923, 2025). "We found that voxel-wise area of perivascular MMP9 in periventricular NAWM and WMH of individuals with hypertension and control individuals positively correlated with larger vessel walls (ρ = 0.323, p < 0.001) and Masson’s staining intensity (ρ = 0.242, p < 0.001)." (PMID 40219923, 2025). "Moreover, following management of the cardiovascularrisk, MMP-9 levels decreased and TIMP-1 levels increased suggesting a potential role for these markers in hypertension." (PMID 37886137, 2023). "Effects of eucalyptol, a key component of eucalyptus globules, on matrix metalloproteinase-9 (MMP-9) and its tissue inhibitor(TIMP-1), compared with lisinopril, were investigated in a model of hypertension induced by chronic intraperitoneal (IP) injection oflow dose nicotine in rats." (PMID 37886137, 2023). "Therefore, it is of interest to evaluate effects of eucalyptol, compared to lisinopril,on systolic blood pressure and plasma levels of MMP-9 and TIMP-1 in a rat model of hypertension induced by chronic exposure tonicotine." (PMID 37886137, 2023). "Additionally, a significant relationship between increased CRP, MMP-9, and MMP-2 levels and systolic hypertension and arterial stiffness was demonstrated." (PMID 35873099, 2022). "The role of circulating MMP-2 and MMP-9 in the etiopathogenesis of essential hypertension has not yet been studied in connection with age." (PMID 33023122, 2020). "The role of MMP-2 and MMP-9 in the etiopathogenesis of essential hypertension is documented in a number of studies, but none of them comprehensively address their age-dependent activation." (PMID 33023122, 2020). "An additional risk factor such as hypertension did not cause significant changes in the levels of MMP-2, MMP-9, and TIMP-4." (PMID 31781384, 2019).
Hypertension (continued). "We next followed up the cases without cardiovascular dysfunction to explore the effect of MMP-9 on the occurrence of hypertension and/or left ventricular hypertrophy in OSAS patients." (PMID 29693002, 2018). "Interestingly, the authors of the present study first reported l-NAME-induced hypertension and vascular remodeling in rats in which there was an up-regulation of MMP-2 and MMP-9 protein expression in response to oxidative stress." (PMID 30347737, 2018). "In our recent study, age, gender and pre-existing hypertension did not influence the plasma levels of MMP-9 and TIMP-1 at any time point." (PMID 30157791, 2018). "Serum MMP9 levels were significantly higher in subjects with hypertension than those without hypertension in each group (all P<0.05)." (PMID 30373522, 2018). "Despite the increased evidence of the important role of matrix metalloproteinases(MMP-9 and MMP‐2) in the pathophysiology of hypertension, the profile of thesemolecules in resistant hypertension (RHTN) remains unknown." (PMID 26039662, 2015). "Activity of MMP-9 was barely detectable by confocal microscopy in normotensive young mice and was not increased significantly by hypertension." (PMID 25677910, 2015). "In addition to MMP-2 and MMP-9, we demonstrate that MMP-13 also plays a significant role in hypertension-induced renal injury." (PMID 24159376, 2013). "Furthermore, stroked SHRs displayed a significant increase in the expression of activated MMP9 compared to their sham counterparts, showing that this was not due to hypertension alone." (PMID 33214598, 2020). "MMP-9 plasma concentrations were also elevated in obese children with and without hypertension." (PMID 30302090, 2018). "Thus it has been suggested that plasma concentrations of MMP-2, MMP-9 and TIMP-1 could serve as markers of cardiovascular remodeling in hypertension or in type 2 diabetic patients where MMP-9 in particular is elevated." (PMID 25535075, 2014). "However, the very tight correlation between MMP9 and MNIC in individual rats (Spearman rho = 1.000 and p<0.05) corroborates our hypothesis that inadequate (E)PC mobilization in hypertension results from compromised NOS activity." (PMID 23554866, 2013). "However, despite the association between increased MMP-9 activation and the genesis of ICH in various experimental murine models, genetic deletion of MMP-9 did not attenuate neurological manifestations associated with hypertension-induced ICH in aged mice." (PMID 35547620, 2022). "Thus, alterations in plasma MMP-9 and TIMP-1 levels are related to a pathological remodeling of target organs as heart, vessels, or kidney during the development of diabetic nephropathy, albuminuria, arterial stiffness, or hypertension, among other pathological situations." (PMID 28791014, 2017). "In VSMCs, CRID3 inhibited collagen synthesis induced by Ang II and CRID3 prevented the increased expression of MMP2 and MMP9 unlike TIMP2, indicating that suppressing NLRP3 inflammasome was a target in aortic fibrosis in hypertension." (PMID 30906225, 2019). "The results of our study may indicate that MMP-2 inhibition is therapeutically applicable during development of hypertension, while in developed, stabilized and uncomplicated hypertension, systemic MMP-2 and MMP-9 inhibition may not be desirable." (PMID 33023122, 2020). "The results of our study may indicate that MMP-2 inhibition is therapeutically applicable during the development of hypertension, while in developed, stabilized and uncomplicated hypertension, systemic MMP-2 and MMP-9 inhibition may not be desirable." (PMID 33023122, 2020).
ischemia (157 papers, 2005 to 2026). A hypoperfusion of the BLOOD through an organ or tissue caused by a PATHOLOGIC CONSTRICTION or obstruction of its BLOOD VESSELS, or an absence of BLOOD CIRCULATION. "Using a focal Middle Cerebral Artery occlusion model, this study demonstrates MMP-9 activation following ischemia, influencing susceptibility to seizures." (PMID 38255970, 2024). "The inflammation also causes a significant elevation of matrix metalloproteinase (MMP-9) which belongs to MMPs—a group of hydrolase enzymes expressed in many overwhelming cases such as wounds, osteoarthritis, ischemia, and infectious diseases." (PMID 36671243, 2022). "We have previously shown that pericytes are involved in very early BBB damage during ischemia, and that the vascular damage near their somata corresponds to rapid increases MMP-9 activity." (PMID 33505320, 2020). "MMP-2 and MMP-9 have been associated with the proliferation and migration of EPCs in ischemia-induced angiogenesis." (PMID 30645596, 2019). "Increased matrix metalloproteinase (MMP)-9 expression also has a known association with ischemia within the brain, with knockout mice displaying increased protection against post-ischemic BBB dysfunction and inflammation." (PMID 32038147, 2019). "Subsequent with the previous studies, it is assumed that the MMP-9 aggravates ischemia and facilitates the infiltration of neutrophils, also causing extracellular matrix degradation due to its unique characteristic from matrix enzyme family." (PMID 30356307, 2018). "During the last 20 years, MMP-9 has been identified as aberrantly overactive in ischemia, potentially causing deleterious effects during ischemia and after RE; therefore its inhibition has been suggested as a potential therapeutic target." (PMID 27445688, 2016). "Gelatinase B/MMP-9 has also been implicated in capillary branching during ischemia-induced revascularisation." (PMID 24473089, 2014). "In a previous study, an emphasis has been placed on the fact that ZO-1, albeit intracellular, is a substrate of MMP-9 while in vivo studies underlined that this substrate was degraded by MMP-9 after ischemia." (PMID 23320797, 2013). "However, two studies reported correlations p > 0.05, albeit early signs of ischemia on brain CT were associated with higher levels of MMP-9 (163 ng/mL [IQR: 110–193] vs. 54 ng/mL [IQR: 38–74], p < 0.001)." (PMID 39091977, 2024). "Our investigation revealed that MMP-9 might associate with the infiltration of neutrophils in MSC therapy after ischemia for the first time." (PMID 29724240, 2018). "Severe BBB disruption is associated with marked elevation of MMP-9 at 24 to 48 h after ischemia." (PMID 26012470, 2015). "Elevated level of ET-1 and MMP-9 might spread from the choroid to the optic disk causing vasoconstriction, ischemia, and blood-brain barrier disruption." (PMID 26697209, 2015). "The increased hemorrhagic risk observed when G-CSF is associated with tPA during the acute phase of ischemia could be directly related to MMP-9 degranulation from these peripheral neutrophils." (PMID 24885160, 2014). "However, pericytes also appear to induce MMP-9 activity during neuroinflammation and ischemia." (PMID 33505320, 2020). "Third, early reperfusion significantly attenuated MMP-9 activities at 3 days post-ischemia thereby preserving tensile strength of the infarcted myocardium." (PMID 40844997, 2025). "HMGB1 mediates the secretion of MMP9, which is involved in early blood–brain barrier degradation and plasma leakage during ischemia via pericytes." (PMID 38740617, 2025). "The effects of ischemic time and therapy on the expression of MMP-9, -3, and -2 were analyzed 24 h after onset of ischemia." (PMID 39273389, 2024).